IL10 (interleukin 10)
Diseases named in the same sentence as IL10 in open-access papers (continued):
Sharing a sentence is not in itself a finding about the gene and the disease.
tumor (continued). "Negative correlations between the frequencies of IL-10-expressing B cells and the frequencies of granzyme A- and perforin-expressing CD4+ T cells were also observed in tumor-infiltrating cells." (PMID 27136203, 2016). "Cisplatin treatment did not inhibit or induce the secretion of IL-10, TNF-α, IFN-γ and TGF-β in the C57BL/7 mice with miR-Sc-overexpressing tumours." (PMID 27147225, 2016). "We observed significantly higher tumor and splenic CD4+ T cell–derived IL17A production in the IL-10−/− B16/F10 mice but not in the TDLN (data not shown)." (PMID 27075020, 2016). "TIL155-C1 and TIL155-C2 secreted GM-CSF, IL-2, and IFN-γ but did not secrete IL-4, IL-10, or transforming growth factor (TGF)-β after exposure to 155mel tumor cells." (PMID 25993655, 2015). "Though, as with the brain, the most recent data suggest that the majority of tumor-infiltrating Tregs in peripheral sites are also nTregs, non-CNS tumors can also elaborate TGF-β, IL-10, and PGE2, which can induce peripheral iTreg conversion." (PMID 26217588, 2015). "The 9 patients with a skin GvHD stage II and III, developed significant increases of IL-6 (P = 0.0010), sIL-2R (P = 0.0049) and TNF-α (P = 0.0020) in the serum, whereas IL-8, IL-10 and IL-1ß did not significantly change." (PMID 26315105, 2015). "Th1 polarization was demonstrated after stimulation with CTA-pulsed DCs and co-culture with tumor cells, by detecting more than 50-fold increase in IFN-γ and TNF-α production and no significant change in IL-4, IL-5, and IL-10 levels, using ELISA." (PMID 25739119, 2015). "Composite results show that daily oral intake of mushroom beta-glucan in tumor-bearing mice can lower the amounts of M-CSF gene expression in the lungs but does not affect the amounts of IL-12, GM-CSF, IFN-γ, IL-6, IL-10, COX-2, and TGF-β in the lungs." (PMID 26167490, 2015). "Tumor infiltrating NK cells purified by negative selection from ascites fluid from ovarian cancer patients produced less IFN-γ and IL-4, but more IL-10 compared to corresponding peripheral blood NK cells." (PMID 25972872, 2015). "Other cytokines analyzed (GM-CSF, IL-2, IL-4, IL-10, IL-12 (p70), IL-13, IL-17, VEGF and TNFα) were below detection level of the assay, or did not exhibit any significant changes upon tumor growth or Delta24-RGD treatment (results not shown)." (PMID 24866126, 2014). "When stimulated by tumor cells and an anti-CD3 antibody, Vγ1 T cells express IFN-γ and GM-CSF, but not IL-1β, TNF-α, IL-12, IL-2, IL-4, IL-10, or TGF-β." (PMID 25538706, 2014). "Hyperactivation of MAPK signaling similarly inhibited IL-12 production and TH1 stimulation by melanoma-altered DC, though these effects were independent of IL-10, TGFβ, VEGF, and PGE2 in tumor lysates." (PMID 23874338, 2013). "The low levels of IL-10 production by CD4+ and CD8+ T cells stimulated by DC/tumor did not impair the production of IFN-γ (data not shown)." (PMID 23555011, 2013). "In the tumor tissue, however, we found only an increased TGF-β1 expression, whereas IL-10 expression was not elevated." (PMID 22674057, 2012). "Although the potential underlying mechanisms are not identified yet, it has been reported that several tumor types, including lung tumors, are able to produce considerable amounts of certain cytokines such as TGF-β, IL-10, or IL-17A." (PMID 22855687, 2012). "However, the tumour cells are also capable of secretion of these factors and may thereby recruit (e.g. by chemokine (C-C motif) ligand 17/22 (CCL17/22)) or lead to the differentiation of immunosuppressive cell types (e.g. by indolamine-2,3-dioxygenase 1 (IDO1) or Interleukin 10 (IL10))." (PMID 22216283, 2011). "Il10−/−; Myd88−/− mice treated with AOM displayed reduced expression of Il12p40 and Tnfα mRNA and showed no signs of tumor development." (PMID 19551144, 2009).
tumor (continued). "IL-2 and IL-13 were not correlated with PR status, whereas IL-1β, IL-6, IL-8, IL-10, IFN-γ, MCP-1, MIP-1β, TNF-α and, to a lesser extent, IL-4, IL-12 and G-CSF were more abundant in PR-negative tumours than in PR-positive ones." (PMID 17261184, 2007). "While some authors have reported that NPC tumor cells do not express IL-10, others observed IL-10 expression in epithelial NPC tumor cells and tumor infiltrating lymphocytes." (PMID 15450122, 2004). "In the spleens of RLS40-bearing mice (tumor node > 1 cm3), the expression of markers corresponding to immunosuppressive phenotype were detected: in addition to PD-L1, the expression of CCL17 but not IL10 was detected." (PMID 40867260, 2025). "Regardless of the degree of tumor-specific or neoantigen-specific TILs, reinfused TILs are still affected by TME-mediated mechanisms, such as IL-10, TGF-β, nitrogen metabolism products, low pH, high lactate, and hypoxia, a challenge faced by any T cell migrating to the TME." (PMID 40458394, 2025). "Whereas INFG and other cytokines, such as IL-6 and IL-10, did not exhibit any significant increase, this implies that the elevated levels of CXCL10 triggered by light may contribute to tumor regression." (PMID 39080467, 2024). "Tumour and peripheral blood MDSCs isolated from human CRC cancer patients potently inhibited T cell proliferation ex vivo, and pharmacological inhibition of IL-10 but not Arg1 of iNOS reversed the immunosuppressive effect of MDSCs in a human CRC study." (PMID 38464388, 2024). "The results of the P815-IFNG tumor models displayed a significant increase in the transcriptional or translational levels of murine IFNG and CXCL10 in the light group, rather than IL-6 or IL-10." (PMID 39080467, 2024). "Some cytokines in TME, such as macrophage colony stimulating factor, IL-4, IL-6, IL-10, TGF-β and VEGF can alter the differentiation of DCs and inhibit the activation and maturation of DCs, resulting in a lack of mature and functional DCs in tumor patients." (PMID 37064113, 2023). "Clustering IL10, TGFβ1 and FOXP3 may also provide a better understanding of the contribution of the regulatory subsets to the systemic immunodeficiency and lack of tumour clearance observed in CLL patients." (PMID 36973425, 2023). "As MDSCs from TLR4KO mice failed to produce IL-10 and were less effective in reducing macrophage production of IL-12, the TLR4 pathway in MDSCs was considered a promising therapeutic target for promoting anti-tumor immune responses." (PMID 37524886, 2023). "Namely, multiple cytokines that promote the M1-to-M2 switch (including IL-5, IL-10, IL-17, IL-22) were higher in the serum of PyMT-bearing mice independent of the presence and absence of TAC, indicating the involvement of tumor properties in inducing this switch." (PMID 37508517, 2023). "Moreover, only IL-10 and BMP4 show modest enhancement of HHLA2 expression in monocytes and dendritic cells, but not in ccRCC tumor cells." (PMID 37891555, 2023). "TAMs are more similar to M2 polarized macrophages, which can promote tumor immune escape by suppressing dendritic cells (DCs) and CD8+ T cells; these effects are mediated by IL-10 or the expression of the negative costimulatory molecules like programmed death-ligand 1 (PD-L1)." (PMID 35733919, 2022). "Indeed, both yeast extract and WGP attenuated tumor growth at the 4th week of the experiments, with the reduction in serum IL-1β and IL-6, but not TNF-α and IL-10, supporting a previous publication." (PMID 36142859, 2022). "Moreover, our results demonstrated that the frequencies of IL-10+CD8+ and IL-4+CD8+ T cells had positive correlations with the tumor size, however the latter was not statistically significant (R = 0.4, P = 0.013, R = 0.3, P = 0.098, respectively)." (PMID 36376825, 2022). "Additionally, when the tumor-bearing MUC1 existed, DCs produced excessive IL10 rather than IL12, even after being stimulated by LPS." (PMID 35883508, 2022).
tumor (continued). "Moreover, none of the IL-10, IFN-γ, or IL-2 level was correlated with tumor size (r = 0.024, p = 0.925; r = −0.115, p = 0.568; and r = −0.232, p = 0.276, respectively)." (PMID 34257554, 2021). "This bias may contribute to immune escape of tumors because T-cell-mediated tumor rejection requires a Th1-driven response involving IFN-γ and IL-12 rather than a Th2-prone milieu, which is promoted by IL-10." (PMID 33141285, 2021). "Besides, IL-2 level in HT treated tumor displayed a slight increase, while the concentrations of TNF-α and IL-10 showed no obvious changes as compared to control group." (PMID 33986437, 2021). "Moreover, contrary to previous reports, high levels of LOX‐1 in the tumor stroma did not correlate with the inhibition of CTL‐derived IFN‐γ and induction of MDSC‐derived IL‐10 expression." (PMID 33675293, 2021). "However, the expression of several anti-inflammatory cytokines, such as CCL17, CCL22, IL-10, and TGF-β, and the M2 marker ARG1, was not significantly changed; these results were consistent with the transcriptome data in H22 tumor-bearing mouse liver tissue." (PMID 33710817, 2021). "To determine whether IL-10 has direct effect on the Ad-hTERT mediated cytotoxicity of tumor cells, we conducted an in vitro Cell Counting Kit-8 (CCK-8) cell viability assay and confirmed the role for IL-10 in the presence or absence of Ad-hTERT infection." (PMID 33717103, 2021). "IL-10-Fc failed to promote expansion and anti-tumour cytotoxic activity of terminally exhausted CD8+ T cells in MPC-KO OT-I CD8+ T cells in both B16F10-OVA tumours and YUMM1.7-OVA tumours." (PMID 34621543, 2021). "Interestingly, FTO depletion restored the expression levels of TNF‐α, IFN‐γ, IL‐10, and TGF‐β, but not on IL‐17 in CAL27‐A formed tumor." (PMID 34378866, 2021). "Clinical and experimental data indicate that, in the large majority of cancers, TAMs acquire an M2-like tumor-promoting phenotype characterized by high levels of immunosuppressive markers (e.g., ARG1, MMR1, IL10), as opposed to low levels of inflammatory cytokines (e.g., IL-12, IL1β, TNFα)." (PMID 32823961, 2020). "Tumor cells, not surprisingly, participate in the MDSC-derived IL-10 regulation." (PMID 32793192, 2020). "In accordance with the high-tumor burden setting, the antitumor effects of all three NGFR isoform-enriched CD44v6 CAR-T cells were accompanied by elevated systemic levels of human IFN-γ, in the absence of IL-6 and IL-10." (PMID 29619024, 2018). "We employed IHC and flow cytometry because the M2 and M1 markers are also ubiquitous enzymes (iNOS and ARG1) and cytokines (IL10 and IL12) which can be expressed by other Iba1(−) cell types (non-TAM, including other immune cells) in the GBM tumor microenvironment." (PMID 30041669, 2018). "In addition, CD163 expression was not elevated in tumor-bearing HSC-NOG-hIL-6 Tg mice (data not shown), and there were no transcripts of VEGF and IL-10 in splenic monocytes in HSC-NOG-hIL-6 Tg mice." (PMID 29456539, 2018). "However, it drew our attention that, whilst having a greater regulatory T proportion, the tumour samples of the BPA-exposed group did not exhibit a greater expression of TGF-β, nor IL-10." (PMID 28874690, 2017). "Furthermore, we found that in contrast to B16scrambled, B16SLC35A1 did not increase IL-10 and TGF-β mRNA levels in the presence of IFN-γ, thus making the tumor micro-milieu of the sialic acid low tumor less tolerogenic." (PMID 26741508, 2016). "Functionally, we demonstrate with the calcein release assay that canine CD3−/NKp46+ cells kill canine tumor cell lines without prior sensitization and secrete IFN-γ, TNF-α, IL-8, IL-10, and granulocyte-macrophage colony-stimulating factor as measured by Luminex." (PMID 27933061, 2016). "Additionally, GARP−/+LAP+ CD4+ T cells made IL-10, and not IFN-γ, and levels of IL-10-secreting CD4+ T cells were elevated in LICRC patients, especially with higher tumor staging." (PMID 26885615, 2016).
tumor (continued). "We did not identify the mechanism leading to DC dysfunction, but tumor cell-derived factors including gangliosides, VEGF, IL-10 and TGF-β may have a role." (PMID 25886502, 2015). "There was no change in the frequency of IL-10-producing B cells in the TDLN, and this proportion is consistent with what is seen in naïve mice of the same age15, suggesting that other mechanisms mediate the tumor-promoting activity of LN B cells." (PMID 26193241, 2015). "Two M2 cytokines (IL-10 and TGF-β) were marginally greater in the tumor/non-trained group than in the tumor/trained group and one cytokine (IL-4) was marginally greater in the tumor/trained group than in the tumor/non-trained group." (PMID 24520305, 2014). "Analysis of the profiles of cytokines in the culture supernatants showed that the tumor-activated γδ T cells secreted substantially more Th1-prone cytokines such as IFN-γ, IL-1, IL-6, and IL-12, but not IL-4 and IL-10, than peripheral-derived γδ T cells did (n = 5)." (PMID 24741609, 2014). "ELISA analysis showed that DRibbles stimulation, similar to LPS, could significantly increase the levels of IL-6, IL-10 and TNF-α, whereas whole tumor cell lysate stimulation could not." (PMID 23326458, 2013). "However, the expression of IL-10 and infiltration of T lymphocytes (e.g., CD3+, CD4+, CD8+) as well as their correlation within tumor tissues are not known, which needs further investigation." (PMID 24116074, 2013). "Indeed, even if some tumor antigen specific CD4 Treg clones were also found to secrete a diverse panel of cytokines such as IFN-γ, GM-CSF, TNF and IL5 or IL4 and IL10, in vitro, none of them was able to secrete IL2." (PMID 23284752, 2012). "PE mice, in fact, secreted IL-10, with no detectable production of IFN-gamma, and, only after administration of IFN-gamma and recombinant IL-12 to newborn mice, cytotoxic activity was restored and a reduction in tumours frequency was achieved." (PMID 22489251, 2012). "Also, in Experiment II, without tumor implantation, the same patterns of expression were observed for TNF-α and IL-10." (PMID 19040745, 2008). "While it has been reported that IL-10 is not expressed by NPC cells as detected by RNA in situ hybridisation, some reports using immunohistochemical and molecular techniques showed the expression of this cytokine by epithelial NPC tumor cells and TIL." (PMID 15450122, 2004). "Notably, GSDMD knockout did not completely inhibit the production of IL-6, tumor TNF-α, and IL-10, suggesting that GSDMD-independent pathways may contribute to inflammation." (PMID 41345109, 2025). "The lower levels of IL-10 cytokines, as well as the increase in TNF found in our study, suggest the M1 activation and M2 inhibition in cells transfected with HPV oncogenes, suggesting higher pro-inflammatory activity and lower anti-inflammatory activity, which does not favor tumor development." (PMID 39599846, 2024). "Modules 1–5 were rich in cytokines (e.g., IL6, IL10), cytokine receptors (e.g., CCR2, CCR4), and immune cell markers (e.g., CD3D, CD3E), indicating that the DEGs primarily regulate the immune microenvironment rather than tumor malignancy traits like proliferation and invasion." (PMID 38594692, 2024). "The immunosuppressive cytokine milieu was rich in IL-10 and TNF-α in HPV-negative but not in HPV-positive HNSCC; the resulting functional impairment of tumor-infiltrating pDCs further supported the immunosuppressive TME by promoting the expansion of Tregs in the tumor tissue." (PMID 39020402, 2024). "In contrast, STING gene silencing does not affect cell viability or apoptosis but promotes IL-10, IDO, and CCL22, thus enhancing immunosuppressive cytokines and regulatory T-cell infiltration, suggesting that STING regulates the TME and influencing tumor progression." (PMID 36936940, 2023).
tumor (continued). "Notably, TECs can express the death mediator Fas ligand following the cooperatively inducing by several factors including VEGF-A, IL-10, and prostaglandin E2 (PGE2), thus obtaining the ability to kill effector CD8+ T cells rather than regulatory T cells (Treg) to enhance tumor cell escape." (PMID 36324128, 2022). "So far, we have identified CXCL1, IL10 and CCL4 in exercise-conditioned serum of advanced PC patients; it will be important to know if these myokines are generally induced by exercise, independent of the tumour type and its characteristics (e.g., aggressiveness or hormone dependency)." (PMID 34359731, 2021). "Properties of quercetin, and other identified compounds, that reduce IL-6 and IL-10 show promise as a potential anti-cancer therapeutic, though reductions in TNF and IL-12 may not be favourable for anti-tumour activity as these cytokines can promote the anti-tumour response." (PMID 32183059, 2020). "In the present study, we found that the expression of IL-4, IL-6, TNF-α, and IFN-γ but not IL-10 dramatically increased after T cell interaction with peptides+HB100-108/pulsed DCs, indicating that this vaccine design has the ability to activate allogeneic T cells against tumor antigen." (PMID 32322595, 2020). "Similarly, in in vivo experiment on Balb/c mice injected with EMT6/P cells, the combination MET+CUR decreased tumor size but only trends for increase of IFN-γ and for significant decrease of IL-4 were detected, while IL-2 and IL-10 level did not change significantly." (PMID 30959898, 2019). "Naturally occurring tumour‐specific HLA‐II‐restricted CD4+ T cells and those engineered to express HLA‐I‐restricted tumour TCRs have been reported to exhibit a mainly Th1 phenotype, where cells typically produce IFN‐γ, TNF‐α and IL‐2 but not IL‐4, IL‐5 or IL‐10." (PMID 27324616, 2017). "In the absence of IL-10, impaired Treg-derived Nrp-1 suppressive functions and Foxp3 expression may be lost, allowing their transformation into effector CD4+ T cells to counteract tumor growth." (PMID 27075020, 2016). "Reconstitution of tumor-bearing BCDM with WT B cells, but not PD-L1−/− or IL-10−/− B cells, could restore tumor growth in oxaliplatin-treated mice, implicating both PD-L1 and IL-10 in mediating the Breg suppressive effects." (PMID 27437104, 2016). "Moreover, we observed that CD204 did not co-localize with immunosuppressive molecules, such as IL-10, B7-H1, or B7-H4, in UCB tissues (data not shown), which suggested that the expression of CD204 on Mφs is sufficient to promote tumor progression independently of other pathways." (PMID 26001293, 2015). "Moreover, the expression levels were unaffected by PDT or RelA knockdown, altogether indicating that IL-10 and IL-12 did not modulate IL-6 and TNF-α signaling and did not play a role in the PDT response by tumor cells or the immunogenicity of PDT-afflicted EMT-6 cells in macrophages." (PMID 26307977, 2015). "IL10 could be a prognostic biomarker of a healthy longevity both in men and women, but only if IFNy and IL6 are correctly functioning in the respective gender: if this condition is not respected IL10 is a biomarker for the tumor progression in both genders." (PMID 24498974, 2014). "The capacity of tumor cells (MCF7 and M628) to induce senescence in naïve CD4+ T cells was investigated in the presence or absence of a panel of neutralizing antibodies against IL-10, TGF-β, TCRαβ, PDL-1, and MHC-class II, as well as the IDO inhibitor, 1-methyl-D-tryptophan (1-MT)." (PMID 25231413, 2014). "However, unlike IL-10 and TGF-β1 mRNA, Ctla-4 transcripts were largely eliminated at 12 days such that at later timepoints, one would expect a diminution of cell surface CTLA-4 and subsequent diminution of Treg inhibition of effector cell clearance of tumor cells." (PMID 34375938, 2021).
tumor (continued). "In this study, miR-138-5p did not affect the expression of VEGF, TGF-β, IL-10, eNOS and PGE2 in NSCLC cells, while targeting and down-regulating PD-L1, indicating that miR-138-5p could affect the function of DCs by decreasing the expression of PD-L1 on tumor cells." (PMID 32754587, 2020).